LRRC8A (leucine rich repeat containing 8 VRAC subunit A)
Diseases named in the same sentence as LRRC8A in open-access papers (continued):
Sharing a sentence is not in itself a finding about the gene and the disease.
psoriasis (1 paper, 2025). An autoimmune condition characterized by red, well-delineated plaques with silvery scales that are usually on the extensor surfaces and scalp. "As psoriasis is a common chronic inflammatory skin disease characterized by disturbed epidermal differentiation and aberrant function of transiently amplifying cells, we investigated the involvement of LRRC8A in this disease." (PMID 40492178, 2025). "Zinc pyrithione, recently identified as an LRRC8A activator, has shown benefits in mild psoriasis." (PMID 40492178, 2025). "Strikingly, immunohistochemical staining of lesional PP indeed showed a strong decrease of LRRC8A expression, whereas the uninvolved skin of patients with psoriasis showed basal localization of LRRC8A and less expression in upper layers, like in healthy epidermis." (PMID 40492178, 2025). "Since psoriasis is mediated by aberrant expression of Th1 cytokines, we investigated whether these inflammatory mediators also interfere with LRRC8A expression." (PMID 40492178, 2025). "Therefore, we hypothesize that aberrant LRRC8A regulation might contribute to the pathogenesis of psoriasis, and hence LRRC8A might represent a promising target for the treatment of PP." (PMID 40492178, 2025).
psoriasis vulgaris (1 paper, 2025). Plaque psoriasis is the most common presentation of psoriasis. "Since we provide evidence for the role of LRRC8A in this cell type, we wondered whether LRRC8A is deregulated in the skin of patients with psoriasis vulgaris." (PMID 40492178, 2025).
renal hypertension (1 paper, 2021). Hypertension caused by the kidney's hormonal response to narrowing or occlusion of the renal arteries. "To determine the functional relevance of LRRC8A in vascular remodeling, we firstly examined the expression level of LRRC8A in basilar artery from 2k2c renal hypertension model." (PMID 34725866, 2021).
status epilepticus (1 paper, 2026). Status epilepticus is defined as a continuous seizure lasting more than 30 min, or two or more seizures without full recovery of consciousness between any of them. "Our data show that neither expression of LRRC8a nor the amplitude of tonic currents was altered 4 h after status epilepticus-induced TLE." (PMID 41684009, 2026).
viral infections (1 paper, 2024). "LRRC8A, a classic channel protein, regulates channel activity and cell volume, directly or indirectly affecting T-cell signaling, and exerts antiviral effects during viral infections." (PMID 39113714, 2024). "Understanding the intricate interactions between LRRC8A and the immune system may lead to the development of novel treatment approaches that effectively address tumor growth and viral infections; however, the ion channel realm is complex." (PMID 39113714, 2024). "Therefore, LRRC8A is a potential immune target against tumor growth and viral infections." (PMID 39113714, 2024).
cancer (33 papers, 2016 to 2026). A tumor composed of atypical neoplastic, often pleomorphic cells that invade other tissues. "LRRC8A is involved in various physiological processes and has been confirmed to be associated with conditions such as cancer, neurological disorders, and metabolic diseases." (PMID 41439137, 2026). "While numerous studies have linked LRRC8A to drug resistance, its role varies across different cancer types." (PMID 41439137, 2026). "Accordingly, high LRRC8A expression was linked with poor prognosis in several cancer types, although databases also reveal inverse correlations for other tumors." (PMID 41419196, 2025). "LRRC8A expression levels might be linked to tumour progression, metastasis, and treatment response, although its implications in different cancer types can be varied." (PMID 38909013, 2024). "The therapeutic significance of targeting LRRC8A varies across different cancer types but shares common potential." (PMID 41439137, 2026). "As a core component of VRAC, LRRC8A plays a crucial role in modulating the efficacy of chemotherapeutic agents in cancer treatment." (PMID 41439137, 2026). "The present study provides novel insights that support the potential of potent and selective LRRC8A inhibitors as therapeutic applications in TAM-targeting cancer immunotherapy." (PMID 39273558, 2024). "Further studies under conditions that mimic the TME are needed to examine the clinical applications and limitations of LRRC8A inhibitors in cancer immunotherapy." (PMID 39273558, 2024). "The results obtained provide novel mechanistic insights into the therapeutic potential of LRRC8A inhibitors in cancer immunotherapy." (PMID 39273558, 2024). "In summary, LRRC8A participates in cancer cell proliferation and migration, cellular immune responses and the entry of chemotherapeutic drugs such as cisplatin or cGAMP, into cancer cells to induce cell death." (PMID 39113714, 2024). "A recent study reported that LRRC8A was upregulated by NSUN2-mediated m5C modification in cancer cells, and m5C-modified LRRC8A mRNA increased RNA stability by binding to YBX1." (PMID 39273558, 2024). "Our meta-analysis infers a conceivable association between LRRC8A - the essential VRAC subunit- expression, and the survival of patients with cancer." (PMID 38909013, 2024). "To highlight the prognostic impact of LRRC8A expression in patients with cancer, we evaluated the Kaplan-Meier analysis to classify samples into groups with high and low LRRC8A expression." (PMID 38909013, 2024). "Most reports have focused on alterations in LRRC8A in tumor cells, indicating its involvement in cancer cell proliferation, migration, death, and multidrug resistance through numerous signaling pathways." (PMID 39113714, 2024). "Downregulation of LRRC8A promoted cisplatin resistance in human ovarian A2780 cancer cells and alveolar A549 adenocarcinoma cells." (PMID 37313175, 2023). "Several m5C-modified mRNAs have been identified as the targets of ALYREF in cancers, such as LRRC8A, Myc, PKM2, and YAP1, among others." (PMID 37537569, 2023). "A previous study found that PI3K/AKT was a downstream signal responsible for the regulatory effects of LRRC8A in cancer cell proliferation." (PMID 36428619, 2022). "VRAC, one of the most important chloride channels located at the cell membrane and constituted by LRRC8A and four other homologous family members LRRC8B–E, has been implicated in each hallmark of cancer." (PMID 36428619, 2022). "Concerning the relevance of the observed correlations for HNSCC, LRRC8A expression is particularly high compared to other cancer subtypes (n = 565) and seems to also depend on the tumors’ anatomical localization." (PMID 34638315, 2021). "Taken together, our data clearly show that TTYH1 and TTYH2 can act as LRRC8A-independent VRACs, suggesting novel therapeutic approaches for VRACs in cancer cells." (PMID 31181821, 2019).
cancer (continued). "Consistent with a previous study of RPE cells, our data confirmed that LRRC8A-independent VRAC currents can be detected in this cancer cell line." (PMID 31181821, 2019). "Recently, the platinum-based chemotherapeutics, cisplatin, and carboplatin have been found to accumulate in cancer cells via the LRRC8A/LRRC8D-containing heteromers, which were downregulated with the development of chemoresistance." (PMID 29868469, 2018). "For platinum-resistant tumors exhibiting low LRRC8A expression, combination therapy with VRAC activators may increase drug uptake, whereas VRAC inhibitors can function as chemosensitizers in cancers where LRRC8A promotes resistance." (PMID 41439137, 2026). "Furthermore, recent research has demonstrated the involvement of LRRC8A in cancer progression, with several studies indicating its overexpression in various cancers and its correlation with drug resistance." (PMID 41439137, 2026). "Moreover, LRRC8A interacts with multiple signaling pathways, which are activated to varying degrees across different cancer types, resulting in context-dependent outcomes for chemotherapeutic sensitivity." (PMID 41439137, 2026). "This phenomenon suggests that LRRC8A may promote intercellular communication within the tumor microenvironment, potentially facilitating cancer cell survival, immune evasion, and the preparation of metastatic niches." (PMID 41439137, 2026). "Additional support for a role of VRAC in cancer comes from studies reporting a positive correlation of LRRC8A expression with poor prognosis in several types of cancer, which, however, has been tentatively attributed to cGAMP-unrelated roles of VRAC in tumor cell proliferation and apoptosis." (PMID 41419196, 2025). "Conversely, LRRC8A promotes proliferation in other cellular states, such as cancer." (PMID 37243831, 2023). "Interestingly, LRRC8A/LRRC8D heterodimer imports the anticancer drug cisplatin in cancer cells to kill them." (PMID 37380989, 2023). "LRRC8A can promote the proliferation and migration of cancer cells in a variety of cancers." (PMID 36632452, 2023). "For instance, overexpression of LRRC8A is responsible for decreased temozolomide resistance in U87/R cells and knockdown of LRRC8A could promote the resistance to Pt-based anti-cancer drugs." (PMID 37313175, 2023). "Because proliferation, migration, invasion, and drug resistance are the main hallmarks of cancer cells, whether LRRC8A knockdown can inhibit the migration, invasion, and drug resistance of PAAD cells in vitro was further investigated." (PMID 36428619, 2022). "Therefore, the critical role and molecular mechanisms of LRRC8A in cancer management need further clarification." (PMID 36428619, 2022). "Analyzing the suggested molecular networks of potential interaction partners of LRRC8A, previously known to be involved in the development of cancer and cisplatin resistance, the Ingenuity Pathway Analysis software indicates that all subunits LRRC8B-E are suggested to be associated with cancer." (PMID 34638315, 2021). "Recent studies indicated that TAM-like M2 macrophages enhanced resistance to anti-cancer drugs and the recruitment of immunosuppressive cells, such as Tregs and myeloid-derived suppressor cells (MDSCs), to the TME, and also that these effects were associated with LRRC8A." (PMID 39273558, 2024). "However, limited information is currently available on the role of LRRC8A in cancer." (PMID 36632452, 2023). "Thus, targeting LRRC8A function might be a promising strategy to improve drug uptake, reduce resistance, and increase the efficacy of chemotherapeutic regimens in resistant cancers, offering a new avenue for improving treatment efficacy." (PMID 41439137, 2026). "While the clinical utility of KCa3.1 activators and LRRC8A inhibitors remains to be fully clarified, the present findings offer new insights that support their potential application in TAM-targeted cancer immunotherapies." (PMID 40806751, 2025).
cancer (continued). "The induction of stress genes like Lrrc8a, Mt1, and Cirbp shows that various types of stress are induced in the MBH during cancer." (PMID 35031523, 2022). "The expression of LRRC8A and four other homologous family members (LRRC8B–E) in pan-cancer was retrieved using the ONCOMINE database." (PMID 36428619, 2022). "LRRC8A networks of cisplatin resistance are suggested to also include NOTCH and SNAI1, which are two transcription factors with high cancer relevance." (PMID 34638315, 2021). "Through starBase (an online tool), NPC2, LRRC8A and NUCB2 were predicted with the strict condition (pan-cancer ≥ 8; degradome data ≥ 3 and clip data ≥ 5)." (PMID 32226311, 2020). "In conclusion, this study unveils a previously unknown complexation event between NPEPPS and LRRC8A proteins, collectively establishing a compelling rationale for targeting NPEPPS to combat cisplatin resistance and enhance chemotherapy efficacy in cancer." (PMID 39671496, 2024). "Interestingly, when either LRRC8A or LRRC8D is knocked out, cancer cells exhibit a higher tolerance towards these platinum-based medications." (PMID 37538172, 2023). "Several studies have reported the potential role of LRRC8A in drug resistance of different cancers, but these observations have not been consistent." (PMID 37313175, 2023). "Also, MICs express another cGAMP or CDN transporter called leucine-rich repeat-containing 8A (LRRC8A)/SWELL1, containing a volume-regulated anion channel (VRAC) subunit along with different tissue-specific cancer cells." (PMID 37380989, 2023). "Although leucine-rich repeat–containing 8A (LRRC8A) has been characterized as a molecular component of VRACs, here we show that Drosophila melanogaster tweety homologue 1 and 2 (TTYH1 and TTYH2) are critical for VRAC currents in cancer cells." (PMID 31181821, 2019). "Targeting KCa3.1 and LRRC8A, along with pathways such as WNK1–AMPK–p38 MAPK and HDAC3, may provide new therapeutic avenues to reeducate and reprogram TAMs within the TME, thereby enhancing the efficacy of cancer immunotherapy." (PMID 40806751, 2025). "Indeed, LRRC8A acts as a positive regulator of cancer cell migration, but how the activity of these channels affect the opening of PANXs, and how LRRC8 protein expression changes during cancer progression is not yet shown." (PMID 34975840, 2021).
tumor (19 papers, 2018 to 2026). "Leucine-rich repeat-containing 8A (LRRC8A; also known as SWELL1), the essential subunit of volume-regulated anion channels (VRACs), is amplified in multiple malignancies and has been implicated in tumor progression and therapeutic resistance." (PMID 41898509, 2026). "The impact of VRAC-mediated cGAMP-efflux from tumor cells and its uptake into cells of the tumor microenvironment was investigated using LRRC8A-deficient tumor cells and recipient mice with selective LRRC8 subunit disruptions, respectively." (PMID 41419196, 2025). "Fascinated by the dual role of LRRC8A/VRAC in tumours, which is linked to both favourable and unfavourable prognoses, our aim was to recognize differentially expressed genes (DEGs) related to LRRC8A to illuminate its functional roles." (PMID 38909013, 2024). "This aligns with our findings where CASC19’s down-regulation in LRRC8A-KO cells is associated with decreased tumor growth." (PMID 38909013, 2024). "The immunohistochemical results of pathological sections obtained from patients with PAAD also demonstrated that the high expression of LRRC8A was associated with a higher tumor grade of PAAD." (PMID 36428619, 2022). "Furthermore, investigations of novel LRRC8A-associated signaling networks, specifically those implicated in metabolic reprogramming, cell cycle dysregulation, and immune evasion strategies, will illuminate its multifaceted contributions to tumor progression." (PMID 41439137, 2026). "Elucidating the correlation between LRRC8A expression levels and tumorigenesis while developing non-invasive methods to detect LRRC8A expression and activity, would enable its utilization as a biomarker for early tumor detection and prognostic evaluation." (PMID 41439137, 2026). "By modulating immune cell functions, LRRC8A enhances anti-tumor immune responses, providing a novel avenue to improve immunotherapeutic strategies." (PMID 41439137, 2026). "In summary, the m5C modification promotes the binding of LRRC8A mRNA to YBX1 through methylation mediated by NSUN2, which enhances the stability of LRRC8A mRNA and promotes the expression of LRRC8A, thereby playing its biological function in tumor cells." (PMID 41439137, 2026). "LRRC8A demonstrates differential expression patterns across diverse tumor types, exhibiting heterogeneous and occasionally antagonistic functions in various malignancies." (PMID 41439137, 2026). "Numerous studies have established that LRRC8A contributes to the progression of multiple malignancies, facilitating tumor development and growth through various signaling pathways and cellular mechanisms." (PMID 41439137, 2026). "The curative effect of radiation therapy depended on tumor-expressed cGAS and was strongly reduced in Lrrc8c−/− mice or in mice carrying DC and T cell specific Lrrc8a disruptions." (PMID 41419196, 2025). "The following sections summarize the role of LRRC8A in T cell development, T cell-mediated immune responses, and tumor adjuvant therapy." (PMID 39113714, 2024). "LRRC8A is crucial for T cell development and function, demonstrating favorable outcomes in antiviral and tumor immunity 10,26,28." (PMID 39113714, 2024). "A comparative analysis of multiple genes revealed that LRRC8A and LRRC8D exhibit higher expression in tumours when compared to other LRRC8 genes, providing an overall characterization." (PMID 38909013, 2024). "Depletion of Lrrc8a or Lrrc8d significantly lowered the tumor response to carboplatin and resulted in a decreased overall survival (OS; P = 0.002 for Lrrc8a, P = 0.0131 for Lrrc8d)." (PMID 36467895, 2022). "cGAMP can be also released by tumor cells and activate neighboring cells following entry via bidirectional transporters like LRRC8A and LRRC8C/E heteromeric channels." (PMID 36280676, 2022). "The immunohistochemical analysis of pathological sections obtained from patients with PAAD demonstrated that a high LRRC8A expression was correlated to the tumor grade of PAAD." (PMID 36428619, 2022).